AHR (aryl hydrocarbon receptor)
Diseases named in the same sentence as AHR in open-access papers (continued):
Sharing a sentence is not in itself a finding about the gene and the disease.
colitis (continued). "We hypothesized that DIM consumption would reduce the severity of DSS-induced colitis and alter associated TLT formation, effects that would be lost in mice with IEC-specific AhR deletion." (PMID 39337636, 2024). "In addition, AhR-activating Lactobacillus has been demonstrated to decrease the severity of colitis." (PMID 38543132, 2024). "However, it is important to note that other proinflammatory and anti-inflammatory mediators during colitis and activation of AhR can also contribute to the regulation of microbiome, including Bacteroides." (PMID 39229279, 2024). "In addition to the Trp metabolites produced by probiotics acting as AhR activators to mitigate colitis, the involvement of other bacterial metabolites has also been observed." (PMID 39517263, 2024). "In addition, given results showing B. acidifaciens can induce a colitis-like phenotype in female GF mice, effect of this species on AhR, ILC3s, and IL-22 specifically in this model should be explored." (PMID 39229279, 2024). "In the DSS-induced colitis animal model, it was found that mice lacking the AhR gene were more susceptible to colitis than wild-type mice." (PMID 39666730, 2024). "Since supplementation with both strains increased the gene expression of AhR and C1P1A1, it was estimated that DSS-induced colitis may have improved through the AhR pathway." (PMID 39517263, 2024). "Gut: Supplementation with L. acidophilus, or its metabolite ILA, attenuates inflammation and restores IL-22 levels through AhR signaling in mice.Similar results were observed in a mice model of DSS-induced colitis supplemented with two strains of ILA-producing B. bifidum." (PMID 38675450, 2024). "This speculation is based on the following facts: treatment with an AHR antagonist substantially abolishes the beneficial effect of 5HIAA on colitis." (PMID 38882491, 2024). "Thirteen studies (k = 13) evaluated the effects of probiotics on AhR signaling in pathological conditions, including colitis (k = 10), celiac disease (k = 1), NEC (k = 1), and intestinal barrier damage (k = 1), with Bifidobacterium emerging as the most commonly used genus (k = 4)." (PMID 39517263, 2024). "In our previous report, we showed a natural product in cruciferous vegetables and ligand of the aryl hydrocarbon receptor (AhR), indole-3-carbinol (I3C), was able to reduce colitis-induced disease severity and microbial dysbiosis in an interleukin-22 (IL-22) dependent manner." (PMID 39229279, 2024). "B. thetaiotaomicron could improve colitis by activating aryl hydrocarbon receptor (AHR) to regulate the differentiation of Tregs and T helper cells." (PMID 38502145, 2024). "Previous studies have demonstrated that microbial indole derivatives can protect against colitis by acting as ligands to bind and activate AhR, suggesting that SH may improve colitis by enriching Alistipes and its metabolite 5HIAA to trigger AhR activation." (PMID 38882491, 2024). "Moreover, both 5HIAA and SH significantly activated the aromatic hydrocarbon receptor (AhR), and the administration of an AhR antagonist abrogated their protective effects against colitis." (PMID 38882491, 2024). "Therefore, with reports showing sex differences in AhR and colitis disease, it will be important to look more closely at how biological sex impacts these factors." (PMID 38397081, 2024). "The activation of AhR by FICZ has also been associated with increased Muc2 expression, a higher number of goblet cells, and a reduction in bacterial infiltration, culminating in the mitigation of DSS-induced colitis." (PMID 38473179, 2024). "Thus, activating AhR pathway is a critical mechanism employed by SCFAs to achieve the anti-colitis activity." (PMID 38257292, 2024). "Accumulating evidence has revealed that AhR can mitigate colitis by decreasing the serum inflammatory cytokines/chemokines (e.g., TNF‐α, IFN‐γ, MCP‐1, and IL‐17), enhancing the expression of IL‐10 and IL‐22, and strengthening the intestinal epithelial cell barrier." (PMID 38882491, 2024).
colitis (continued). "The focus of the current report, after identifying ILC3s/T cells as a major source of IL-22 during colitis, was to target AhR deletion in these specific cell types, assess IL-22 production, and determine how this impacted Bacteroides abundance in the gut during colitis." (PMID 39229279, 2024). "Additionally, other AhR ligands such as Baicalein, NOR, Alpine, and Laquimod metabolites were also found to directly influence Treg differentiation of Tregs, offering potential alleviation of colitis through AhR pathway activation." (PMID 39211042, 2024). "Additionally, activation of AhR by I3C has been shown to reduce TNBS- or DSS-induced colitis and alleviate microbial dysbiosis resulting from colitis, and this effect occurs in an IL-22-dependent manner." (PMID 39767818, 2024). "Indole compounds, which are Trp metabolites derived from intestinal microorganisms, play an important role in intestinal homeostasis by liganding with AHR and are related to the pathogenesis of intestinal diseases such as inflammatory bowel disease and colitis." (PMID 38299316, 2024). "Existing literature suggests that IEC-specific AhR-KO worsens DSS-induced colitis." (PMID 39337636, 2024). "In fact, studies have shown that the increased level of IL-22 induced by AhR agonists, along with the reduction in IFNγ in mononuclear cells of lamina propria, determines healing from chemical and T cell transfer-model-induced colitis." (PMID 38543132, 2024). "Short-chain fatty acids (SCFAs) promote the production of IL-22 by CD4+ T cells during colitis, which is mediated by the induction of butyrate production via the AHR, which is a function of gut microbiota-derived metabolites that regulates intestinal homeostasis." (PMID 38388542, 2024). "This is consistent with our previous research results that IAA released by indole acetylated starch in colon, and the remission effect on colitis may be closely related to the activation of the AHR/IL-22 pathway." (PMID 39458442, 2024). "However, data have shown that the use of anti-miR-124 treatment alleviated intestinal inflammation by inhibiting AhR in experimental TNBS-induced colitis." (PMID 36768556, 2023). "Furthermore, animal studies have reported that AhR deficiency aggravates inflammation in T cell transfer- and DSS-induced mice colitis and that it induces colitis by reducing IL-22 release." (PMID 37554552, 2023). "When compared to AHR homozygous mice, symptoms of colitis were dramatically ameliorated in AHR heterozygous mice, indicating that overstimulation of AHR may contribute to the development of colitis." (PMID 37179416, 2023). "In murine models, AHR-deficient mice (AHR−/−) were more sensitive to dextran sodium sulfate (DSS)-induced colitis, showed higher levels of pro-inflammatory cytokines than wild-type (WT) (namely AHR+/+) controls, and more severe colitis-related symptoms and clinical outcomes." (PMID 37942478, 2023). "The role of AhR on colitis and bacterial infection is increasingly brought on stage." (PMID 36678175, 2023). "It has been indicated that AhR activated by endogenous ligands could inhibit the NF-κB pathway in bronchitis, periodontitis and colitis." (PMID 36721094, 2023). "For example, decreased gut microbiota metabolism of tryptophan leads to less aryl hydrocarbon receptor activation and intestinal inflammation exacerbation, Eggerthella lenta worsens colitis through metabolizing steroidal glycosides and driving Th17-dependent autoimmunity." (PMID 37197204, 2023). "In terms of affecting intestinal inflammation, AHR activation could significantly inhibit the intestinal inflammatory response and alleviate the symptoms of colitis in experimental animals." (PMID 37179416, 2023). "In DSS-induced colitis mice, AHR activation downregulates IL-7 and reduces inflammation." (PMID 37179416, 2023).
colitis (continued). "A recent study showed that mice with AHR repressor deficiency in the IELs were susceptible to infection with Clostridium difficile and DSS-induced colitis because excessive AHR signaling lead to oxidative stress and ferroptosis of the IELs and suppression of the intestinal immune responses." (PMID 37191444, 2023). "Studies have also shown that AHR expression or activation attenuates colitis in mouse models." (PMID 37755265, 2023). "Products of microbial metabolism can activate AhR and upregulate IL-22 production, leading to increased AMP and mucin production in IECs which in turn contribute to reduced colitis susceptibility and may shape microbiome composition and function." (PMID 36894983, 2023). "In addition, microbial tryptophan metabolites signal through AhR to increase IL-22 secretion by innate-like lymphoid cells and T cells, leading to protection from chemically induced colitis." (PMID 37072819, 2023). "As AhR-deficient intestinal Tregs express more inflammatory cytokines like IL-17 and IFN-γ, this study demonstrated the importance of AhR signaling in Treg cells for intestinal homing, and its requirement for their immunosuppressive function in colitis." (PMID 36875083, 2023). "Indigo alleviated murine colitis by activating AHR signaling." (PMID 37179416, 2023). "Similar to other polysaccharides, we found that HSH and BHR have significant modulatory effects on AAA metabolism, especially tryptophan metabolism, and thus may modulate AHR and improve immunity, ultimately achieving their therapeutic effect on colitis." (PMID 37351508, 2023). "In short, IL-7 blockade mediates the favorable impacts of AHR pathway activation on colitis." (PMID 37179416, 2023). "However, probiotics-produced AHR agonists have been successfully used to dampen inflammation in colitis." (PMID 37942478, 2023). "Indole derivatives confer protection in murine models of colitis, largely via AhR activation, leading to increased IL-22 production by ILC3s and T cells that drives improved intestinal barrier integrity, reduced inflammation, and, ultimately, disease amelioration." (PMID 36894983, 2023). "The role of AhR in colitis and bacterial infection is increasingly brought on stage." (PMID 36672703, 2023). "Taken together, this suggests that the increased sensitivity of Ahrdbd/dbd mice to DSS-induced colitis is due to the expression of DNA-binding deficient AHR rather than reduced ligand affinity of AHRdbd compared with AHRwt protein." (PMID 36519841, 2023). "The interaction of FICZ with the AhR could also protect against goblet cell depletion and decreased mucus production during experimental colitis by promoting goblet cell differentiation through the AhR-p-ERK 1/2-mediated mechanism." (PMID 37509654, 2023). "The positive effect of AHR agonists in colitis models has also been proved." (PMID 37942478, 2023). "Briefly, alpinetin directly promoted Treg differentiation in CD4+T cells of mesenteric lymph nodes (MLNs), restored Th17/Treg balance in colons, and then inhibited symptoms of colitis in vivo through elevating AhR expression and coordinating miR-302/DNMT-1/CREB signaling pathway." (PMID 35185569, 2022). "Because PARP7 negatively regulates AHR and IFN-I signaling, we hypothesized that the loss of PARP7 expression would improve therapeutic outcomes in the DSS model of colitis." (PMID 35055106, 2022). "In addition, western blotting results revealed multiple functions of RSBDP in the DSS-induced colitis which were exerted by anti-inflammatory and pro-apoptotic activities, relying on the AhR/CYP1B1 and AKR1C1/PI3K/AKT pathways." (PMID 36145261, 2022). "Additionally, it was shown that AhR was important for T reg cells gut homing and function, and AhR-expressing T reg cells have enhanced suppressive activity in a model of colitis." (PMID 36159798, 2022). "In addition, tetrandrine, a plant-derived natural agonist of AhR, downregulated miR-429 expression in a colitis mouse model." (PMID 35626744, 2022).
colitis (continued). "Notably, anti-miR-124 treatment of TNBS-induced colitis mice improved colitis scores, including a decreased disease activity index and proinflammatory cytokine expression, through AHR modulation." (PMID 35887337, 2022). "In addition, in the presence of L-fucose, IL-22 and its related transcription factor AHR were significantly elevated in the colons of colitis mice." (PMID 36432480, 2022). "A recent study indicated that the aromatic compounds in coffee could promote the expression of CYP1A1 and CYP1B1 by activating AhR, which alleviates experimental colitis." (PMID 36145261, 2022). "In addition, the microbial metabolite Urolithin A (20 mg/kg) mitigates DSS-induced acute colitis through its gut barrier protective and anti-inflammatory activities in an aryl hydrocarbon receptor-dependent manner." (PMID 36558542, 2022). "Moreover, a few studies demonstrated that quercetin cannot alleviate the symptoms of colitis in AhR−/− mice." (PMID 36145261, 2022). "The plant-derived indole, I3C, has been shown to bind to the aromatic hydrocarbon receptor (AhR) found in most tissues, including the gut where it decreases colitis by reducing microbial dysbiosis and boosting the abundance of butyrate-producing Gram-positive bacteria in an IL-22–dependent way." (PMID 35631553, 2022). "The purpose of this study was to investigate whether the activation of AhR can induce tolerogenic DCs (tolDCs) and the differentiation of regulatory T (Treg) cells, as well as ameliorate experimental colitis." (PMID 35461286, 2022). "Accordingly, studies using AhR-deficient mice have shown that impaired AhR activity correlates with diminished levels of IL-22–producing ILC type 3 (ILC3) and consequently culminates in a worsening of inflammatory diseases, such as colitis." (PMID 33924971, 2021). "For example, Lactobacillus could mitigate colitis by producing aryl hydrocarbon receptor agonists (AHR)." (PMID 34490327, 2021). "The suppression of aryl hydrocarbon receptor (AHR) protein and TJ proteins by miR-124 was associated with intestinal barrier disruption in both the 2,4,6-trinitrobenzene sulfonic acid (TNBS)-induced colitis mouse model and CD patient mucosal biopsy samples." (PMID 34943865, 2021). "Although the reduction of MPO expression by Q and the I3C metabolite DIM has already been reported in another mouse model of DSS colitis, in the present work, we could demonstrate that these effects were AhR-dependent." (PMID 33668818, 2021). "Additionally, oral administration of indole-3-ethanol, indole-3-pyruvate, and indole-3-aldehyde mitigates DSS-induced colitis by securing the TJ barrier in an AhR-dependent manner." (PMID 33968085, 2021). "AhR deletion in intestinal mucosa CD11c+dendritic cells and certain macrophage subsets increases the stem cells in the ileal epithelium and differentiates epithelial precursors, causing greater susceptibility to murine DSS-induced colitis." (PMID 34122415, 2021). "Furthermore, indole-3-aldehyde produced by lactobacilli has AhR agonistic activity and protects against candidiasis and colitis in an AhR-dependent manner." (PMID 33963922, 2021). "Importantly, AhR activation in intestinal epithelial cells is also involved in barrier repair during colitis." (PMID 34093534, 2021). "Several studies have determined that AhR exhibits protective effects during intestinal inflammation; with TCDD-treated and FICZ-treated mice ameliorating colitis severity, which were determined from corrected weight loss, reduced colitis symptoms and recover periods." (PMID 32456012, 2020). "Administration of some strains of L.reuteri alone or in combination with other Lactobacillus strains has been reported to prevent DSS-induced colitis in mice due to various mechanisms and some studies suggest that AHR activation and enhanced IL-22 production play a critical role in the process." (PMID 33193381, 2020).
colitis (continued). "In conclusion, our study suggested that baicalein could protect mice from DSS-induced colitis, and its therapeutic mechanism may be related to the regulation of Th17/Treg differentiation via AhR activation." (PMID 33082710, 2020). "I3C may also act through the regulation of gut microbiota, as shown in a recent study in which AhR activation by I3C led to increased production of butyrate and attenuation of colitis." (PMID 33105907, 2020). "Indeed, its link to the NLRP3 inflammasome also validates the role AhR can play in the treatment of colitis in IBD and CAC." (PMID 32456012, 2020). "The role of AhR in inflammatory and autoimmune diseases, particularly in colitis and MS, is receiving significant recognition, which means that there is substantial opportunity to target AhR using ligands to prevent and treat inflammatory and autoimmune diseases." (PMID 33105907, 2020). "Furthermore, fecal microbiota transplantation (FMT) and indigo naturalis (IN), a traditional herbal medicine used for UC, can attenuate DSS-induced colitis in mice by up-regulating the expression or activity of AHR." (PMID 33193381, 2020). "Thus, defects in AhR signaling have been shown to trigger colitis and intestinal bowel disease both in humans and in experimental animals." (PMID 33348596, 2020). "Interestingly, study conducted on a mouse model of induced-colitis revealed that FICZ prevents intestinal barrier function via AhR activation by suppressing IL-6 and claudin-2 expression." (PMID 32899152, 2020). "Similarly, mice treated with an AhR agonist or with Lactobacillus strains with high AhR-ligand production capacity exhibited improvement in symptoms of colitis and metabolic syndrome." (PMID 32487227, 2020). "This viewpoint is also supported by recent literature showing that miR‐124 might aggravate colitis by inhibiting the aryl hydrocarbon receptor in CD." (PMID 33040455, 2020). "Interestingly both, AhR and AhRR-deficient mice are highly susceptible to DSS-induced colitis, which is likely due to the highly cell type specific expression of the AhRR and the resulting cell type-specific differences in AhR/AhRR signalling." (PMID 32366032, 2020). "Dextran sodium sulfate (DSS)-induced colon inflammation is inhibited by multiple AhR ligands, including TCDD; the inflammatory responses and genes associated with skin inflammation (Psoriasis-like) were inhibited the AhR agonist FICZ." (PMID 32932962, 2020). "These reversed colitis effects were due to a change in their cytokine environment, with AhR-activated mice having a reduction in the expression of pro-inflammatory mediators; such as IL-6, IL-12, IL-17, IFN-c, MCP-1, exotaxin-1 and TNF-α, but an increase in IL-22 and TGF-β." (PMID 32456012, 2020). "Similarly, the DHA-induced decrease in the PU.1 and AHR protein expression in LPMCs of mice with OXA-induced colitis was ameliorated, along with the decrease in T-bet and RORγt in TNBS colitis mice when HO-1 was inhibited." (PMID 31284478, 2019). "Within the intestine, AhR is necessary for normal Th17 development, however, in colitis, TCCD may decrease Th17 differentiation." (PMID 30944419, 2019). "Impairment of proper ligation of AHR leads to the development of colitis." (PMID 29866992, 2018). "Therefore, we worked to investigate the anti-colitis efficacy of alpinetin, and explore the key mechanisms from angle of activating AhR and recovering Th17/Treg balance." (PMID 30166541, 2018). "Then, endogenous IAA combines with AHR and intestinal AHR ligands promote AHR transport into the nuclei of Treg cells, promoting release of anti-inflammatory factors, thus helping to alleviate the inflammation of the colitis induced by DSS in mice." (PMID 30197631, 2018). "Furthermore, Chinen and colleagues reported that myeloid AhR is dispensable for inflammatory response in DSS-induced colitis by utilizing the same LysMCre strategy." (PMID 30455703, 2018).